METTL8 (methyltransferase 8, tRNA N3-cytidine)
Diseases named in the same sentence as METTL8 in open-access papers:
METTL8 is named in the same sentence as 22 diseases in open-access papers, as found by Europe PMC text mining. Sharing a sentence is not in itself a finding about the gene and the disease. The quoted sentences say what the papers report.
breast carcinoma (6 papers, 2021 to 2026). "METTL8 expression is elevated in breast cancer, and knockdown of METTL8 inhibits tumor cell growth and strongly blocks tumor cell migration." (PMID 39289775, 2024). "Since the regulation of gene expression by transcription factors (TFs) has very dynamic mechanisms in which various TFs are orchestrated, we endeavored to determine the major regulator of METTL8 expression in breast cancer." (PMID 34063990, 2021). "To validate the regulation of YY1 on METTL8 transcription in breast cancer, we tested the expression level of METTL8 mRNA in silenced YY1 conditions." (PMID 34063990, 2021). "Collectively, the up-regulation of METTL8 in breast cancer is not limited to specific cell types and also occurs in various cancers, including canine mammary tumors in dogs." (PMID 34063990, 2021). "In this study, we confirmed that METTL8 was increasing in breast cancer of human and dog, and revealed its functional roles." (PMID 34063990, 2021). "Although it still has some limitations such as not directly showing the mRNA methylation of ARID1A and modulation of PI3K-AKT pathway via METTL8, this study can be an important clue to better understand the epigenetic regulation of breast cancer." (PMID 34063990, 2021). "METTL8 expression was up-regulated in most human breast cancer cell lines tested and decreased by Yin Yang 1 (YY1) transcription factor knockdown, suggesting that YY1 is a regulating transcription factor." (PMID 34063990, 2021). "Collectively, our study indicates that METTL8 up-regulated by YY1 in breast cancer plays an important role in cancer cell migration through the mRNA modification of ARID1A, resulting in the attenuation of its translation." (PMID 34063990, 2021). "We conducted our study based on the similarity between human breast cancers and canine mammary tumors and elucidated the role of METTL8 in human breast cancer." (PMID 34063990, 2021). "When compared the RNA expression levels in six different breast cancer subtypes, (Her2+, basal, Luminal, Luminal_A, Luminal_B, and triple-negative), METTL8 is evenly expressed in all of them." (PMID 34063990, 2021). "In conclusion, this study presented a new role of METTL8 in breast cancer and identified possible mechanisms." (PMID 34063990, 2021). "Taken together, these results indicate that knockdown of METTL8 reduces breast cancer cell proliferation and migration in vitro." (PMID 34063990, 2021). "In this study, we found that METTL8 expression was significantly up-regulated in canine mammary tumor and investigated its functional roles in the tumor process, including cancer cell proliferation and migration." (PMID 34063990, 2021). "However, METTL8 has been identified as an oncogene in cancer, and a recent report showed that METTL8 knockdown inhibits breast cancer cell growth and strongly blocks breast cancer cell migration." (PMID 39019857, 2024). "This may support our result showing that, instead of STAT3, YY1 is a more important transcription factor regulating METTL8 expression in breast cancer." (PMID 34063990, 2021). "To investigate whether METTL8 interacts with ARID1A mRNA in breast cancer cells, we performed an RNA immunoprecipitation assay (RIP)." (PMID 34063990, 2021). "We then finally chose ARID1A based on the discrepancy between the expression level of mRNA and protein in breast cancer and canine mammary tumor databases because the function of METTL8 is mRNA methylation, which is known to result in restrained protein expression." (PMID 34063990, 2021). "Furthermore, we showed how METTL8 affects the phenotype of breast cancer cells by identifying ARID1A as a target gene for METTL8." (PMID 34063990, 2021). "In this study, we investigated the functions of METTL8 in breast cancer." (PMID 34063990, 2021). "Importantly, cancer cell migration was also significantly impeded by METTL8 knockdown in both breast cancer cell lines." (PMID 34063990, 2021).
breast carcinoma (continued). "Although it has been suggested that STAT3 is the regulator of METTL8 gene expression in mouse embryonic development, it is an important result of showing that METTL8 expression in humans, especially in breast cancer conditions, is caused by not STAT3, but the YY1 transcription factor." (PMID 34063990, 2021). "STAT3 suggested as a METTL8 transcription factor in the previous study, is shown to have a lower correlation than YY1 in breast cancer." (PMID 34063990, 2021). "Although transcription factor YY1 regulates METTL8 expression in breast cancer cells and STAT3 transcriptionally activates METTL8 in mouse embryonic stem cells, the upstream regulator of METTL8 in GBM remains unknown." (PMID 38744809, 2024). "In addition, when we compared the correlation of the gene expression patterns between METTL8 and putative transcription factors, YY1 showed a better correlation coefficient in breast cancer compared to other putative transcription factors." (PMID 34063990, 2021). "In addition, the cancer cell migration and proliferation functions of METTL8 that increase the mortality rate and promote metastasis in breast cancer have not been demonstrated yet." (PMID 34063990, 2021).
pancreatic cancer (6 papers, 2022 to 2025). "Although METTL8 is highly expressed in a variety of cancers, patient survival is only associated with high METTL8 levels in pancreatic cancer." (PMID 39019857, 2024). "METTL8 has been identified as a potential biomarker in hepatocellular carcinoma, and high levels have been associated with improved patient survival in pancreatic cancer." (PMID 37868033, 2023). "Since an increase in METTL8 is associated with increased respiratory chain activity, the obvious benefit to pancreatic cancer cells may be a better supply of energy, allowing for rapid and aggressive progression." (PMID 39019857, 2024). "Similarly, METTL8-mediated m3C32 modification of mt-tRNAs optimizes tRNA structure and mitochondrial translation, with METTL8 overexpression associated with aggressive pancreatic cancer cells." (PMID 38377789, 2024). "Deletion of METTL8 compromises the functionality of the mitochondrial respiratory chain and is correlated with both pancreatic cancer cell proliferation and patient survival." (PMID 39019857, 2024). "The m3C32 modification of mitochondria tRNASer and tRNAThr were catalyzed by the mitochondrial protein METTL8 and the high expression of METTL8 contributed an enhanced respiratory chain activity in pancreatic cancer." (PMID 36266694, 2022). "have found that knockout of METTL8 in a pancreatic cancer cell line can reduce cell growth." (PMID 35247384, 2022).
glioma (3 papers, 2022 to 2024). A benign or malignant brain and spinal cord tumor that arises from glial cells (astrocytes, oligodendrocytes, ependymal cells). "In multiple patient cohorts, METTL8 expression is also significantly higher in high-grade than low-grade gliomas." (PMID 38744809, 2024). "In vitro experiments have shown that knocking down METTL8 can significantly inhibit the proliferation and promote apoptosis of glioma cells." (PMID 38824202, 2024). "To explore transcriptional activators of METTL8 in glioma, we conducted correlative analysis of METTL8 expression with that of established GBM-relevant transcription factors in gliomas using TCGA, NCI REMBRANDT and Gravendeel datasets." (PMID 38744809, 2024). "High expression of METTL8 in GBM is attributed to histone variant H2AZ-mediated chromatin accessibility of HIF1α and portends inferior glioma patient outcome." (PMID 38744809, 2024). "All those results indicated that METTL8 was an oncogenic gene of glioma." (PMID 38824202, 2024). "Future research should delve into whether METTL8 mediates malignant progression of glioma through tRNA or mRNA m3C modification." (PMID 38824202, 2024). "Furthermore, we also assess the effect of METTL8 on apoptosis for glioma." (PMID 38824202, 2024). "Results revealed that TRMT2B, TRMT11, METTL8, TRMT6, and TRUB2 were upregulated in glioma, while METTL6 was downregulated." (PMID 38824202, 2024). "In glioma cells, it was observed that the expression of genes related to MRM, like GTPBP3, METTL2A, METTL6, METTL8, NSUN4, and TRMT61A, showed positive correlation with the expression of HAVCR2, PVR, TNFRSF25 and TNFSF15 as revealed by scRNA-seq analysis." (PMID 38824202, 2024). "The expression of HAVCR2, PVR, TNFRSF25, and TNFSF15 showed a positive correlation with the expression of numerous MRM-related genes like GTPBP3, METTL2A, METTL6, METTL8, NSUN4, and TRMT61A in glioma cells." (PMID 38824202, 2024). "These mechanistic findings, along with the intimate link between METTL8 levels and the HIF1α/RTK/Akt axis in glioma patients, guided us to propose a HIF1α/Akt inhibitor combination which potently compromises GSC proliferation/self-renewal in vitro." (PMID 38744809, 2024). "METTL8 high expression was related to poor prognosis in Bladder Urothelial Carcinoma (BLCA), Kidney renal papillary cell carcinoma, Brain Lower Grade Glioma, LUAD and Thyroid carcinoma." (PMID 36266694, 2022). "We have also validated the co-expression of METTL8 and GFAP in gliomas, and the results indicate that METTL8 might be involved in the localized expression of GFAP." (PMID 38824202, 2024).
Lung Squamous Cell Carcinoma (3 papers, 2021 to 2025). "Moreover, METTL8 itself has been implicated in CD8+ T cell infiltration in lung squamous cell carcinoma, suggesting a broader role in regulating immune responses within tissue microenvironments." (PMID 40918096, 2025). "METTL8 show lower alteration frequency of 3% in Ovarian serous cystadenocarcinoma, 3% in Cholangiocarcinoma, and 2% in Lung squamous cell carcinoma." (PMID 36266694, 2022).
colorectal cancer (2 papers, 2020 to 2022). A primary or metastatic malignant neoplasm that affects the colon or rectum. "Clinically, based on published datasets in human patients with colorectal cancer, high level of METTL8 significantly has a lower survival rate than the low-level cohort (n = 504, p = 0.0024), indicating METTL8 may contribute to therapeutic response in patients with cancer." (PMID 32199293, 2020).
pancreatic adenocarcinoma (2 papers, 2024). "Similarly, the mitochondrial m3C methyltransferase METTL8 has been linked to severe pancreatic adenocarcinoma and colon cancer and is involved in neurogenesis." (PMID 38918637, 2024).
anaplastic astrocytoma (1 paper, 2024). "To validate this result, we performed immunofluorescence staining on oligodendroglioma and anaplastic astrocytoma tissue to assess the expression of METTL8 and GFAP." (PMID 38824202, 2024).
breast invasive carcinoma (1 paper, 2024). "The N3-methylcytidine (m3C) gene, METTL2A, is highly expressed in breast invasive carcinoma (BRCA), and differential analysis showed that METTL2A was differentially expressed in cancer and paracancerous tissues more strongly than METTL6 and METTL8." (PMID 39289775, 2024).
depression (1 paper, 2022). "We found less evidence that METTL8 and DCAF17 were involved in the depression and complex microbiota interaction." (PMID 36699448, 2022).
lung carcinoma (1 paper, 2021). "Finally, we found that the METTL8 levels were increased in multiple lung cancer cell lines and LSCC tissues." (PMID 33816462, 2021). "The results showed that the prognostic value of METTL8 and HSPB3 was significantly available for lung cancer patients." (PMID 33816462, 2021). "The results indicated that METTL8 and ERLIN2 were significantly and negatively correlated with the prognosis of lung cancer patients." (PMID 33816462, 2021).
non-small cell lung carcinoma (1 paper, 2026). A group of at least three distinct histological types of lung cancer, including non-small cell squamous cell carcinoma, adenocarcinoma, and large cell carcinoma. "In anti-PD-1 responding non-small cell lung cancer patients, Mettl8 and the stemness factor TCF7 were downregulated." (PMID 41891923, 2026).
Thyroid carcinoma (1 paper, 2022). "In contrast, there was down-regulation of these four genes in Kidney Chromophobe (KICH), Kidney renal clear cell carcinoma (KIRC), and Thyroid carcinoma Compared to METTL8, the other three genes (METTL2A, METTL2B and METTL6) exhibited a more homogenized co-expression in various cancer types." (PMID 36266694, 2022).
cancer (12 papers, 2020 to 2026). A tumor composed of atypical neoplastic, often pleomorphic cells that invade other tissues. "To identify putative METTL8 target transcripts associated with cancer cell proliferation and migration phenotypes, we surveyed the literature fulfilling three criteria: (i) tumor suppressor genes, (ii) METTL8 binding transcripts and (iii) genes associated with cancer cell migration." (PMID 34063990, 2021). "METTL8 is a methyltransferase that catalyzes RNA base modifications, including m3C and m6A, and has been shown to promote cancer cell migration through direct interaction with ARID1A, a key chromatin remodeler." (PMID 41516402, 2026). "In fact, this mechanism is crucial for the tumorigenicity of colon cancer cells in xenograft mouse models, suggesting a potential role for targeting METTL8 in therapeutic responses for cancer patients." (PMID 38476632, 2024). "The m3C associated genes showed aberrant expression in 17 cancer types for METTL2A, 15 cancer types for METTL2B, 14 cancer types for METTL6 and 13 cancer types for METTL8." (PMID 36266694, 2022). "The differential expression analysis of METTL2A, METTL2B METTL6 and METTL8 was conducted between tumor tissue and normal tissue in 24 different cancer types." (PMID 36266694, 2022). "Notably, METTL8 is a methylase involved in epitranscriptomic regulation in cancer, tumor cell migration, and tumorigenesis." (PMID 41516402, 2026). "Although METTL8 is overexpressed in numerous cancer types, little is known about what contributes to aberrant METTL8 expression in GBM and which METTL8 isoform(s) may influence GBM cell fate and malignancy." (PMID 38744809, 2024). "Even though the role of METTL8 in cancer has been confirmed, whether METTL8 is dominated by mRNA or m3C modification of mt-tRNA in cancer cells still needs to be further studied." (PMID 39019857, 2024). "Overall, METTL8 expression was higher in all the cancer cell lines than in the normal cell line." (PMID 34063990, 2021). "We also demonstrated that METTL8 can affect the proliferation and migration of cancer cells." (PMID 34063990, 2021). "Similarly, but slowly in MDA-MB-453, knockdown of METTL8 decreased cancer cell migration up to 30% at the 48 h time point." (PMID 34063990, 2021). "Thus, the proper maintenance of mitochondrial tRNA folding by METTL8-dependent modification could be important for cancer cell metabolism and homeostasis." (PMID 35247384, 2022). "METTL7A has protein interactions with cancer-related genes BCAS1 and GLIPR1L2, as well as post-transcriptional regulatory genes METTL8 and DDX55." (PMID 37547717, 2023). "We also detected the METTL8 level in normal lung tissues, para-carcinoma tissues, and LSCC tissues, which indicated that the METTL8 level was obviously increased in LSCC compared with that in the normal lung tissues and para-carcinoma tissues." (PMID 33816462, 2021). "While the direct interconnection between increased METTL8-mediated mt-tRNA methylation and protein synthesis has not been explored in cancer, other isoforms of METTL8 have been shown to modify nucleolar RNAs, contributing to the formation of regulatory R-loops." (PMID 38476632, 2024). "The expression levels of METTL8 in most breast cancers are upregulated, mediated by the transcription factor Yin Yang 1 (YY1), which in turn modify AT-rich interactive domain-containing protein 1 A (ARID1A) to promote tumor growth and the migration of cancer cells." (PMID 34862464, 2021).
tumor (9 papers, 2020 to 2026). "In murine models, Mettl8 deletion restrained tumor progression by driving TPEX differentiation into effective Int-TEX cells." (PMID 41891923, 2026). "METTL8 silencing led to a profound reduction in tumorsphere formation, colony formation and tumor initiating cell frequency of independent two GSC lines." (PMID 38744809, 2024). "Moreover, the tumor sizes and weights in the METTL8 KD group were obviously decreased compared with those in the NC." (PMID 33816462, 2021). "The knockdown of METTL8 attenuated tumor cell growth and strongly blocked tumor cell migration." (PMID 34063990, 2021). "METTL8 depletion impairs the ability of GSC to self-renew and differentiate, thus retarding tumor growth in an intracranial GBM xenograft model." (PMID 38744809, 2024). "Pharmacological Mettl8 inhibition promoted TPEX-to-Int-TEX differentiation and tumor control." (PMID 41891923, 2026). "Using a published single-cell RNA-Seq dataset of human GBM, we further show that METTL8 is heterogeneously expressed in GBM; with overall higher METTL8 expression in GBM than non-GBM cells within the tumor microenvironment." (PMID 38744809, 2024). "Interestingly, compared with METTL8 and METTL6, differential expression of METTL2A in BRCA tumor tissues and adjacent normal tissues was more significantly." (PMID 36266694, 2022). "Taken together, these results indicated that METTL8 expression was enhanced in LSCC, which could promote tumor growth dependent on PCNA, c-myc, and Cdc25c." (PMID 33816462, 2021). "Furthermore, the relationship between METTL8 and FOXP3 may be a main role in tumor immune escape for LSCC patients." (PMID 33816462, 2021). "Next we showed in immunodeficient mice xenograft models that METTL8 KO HCT116 cells and their mutants, METTL8ΔSAM and METTL8K80R, are less tumorigenic than their wild-type counterpart and their difference in tumor volume is deemed to be significant (n = 4, ∗∗p < 0.01, ∗∗∗p < 0.005)." (PMID 32199293, 2020). "However, whether METTL8 and GFAP co-localize in tumor cells or astrocytes requires further study." (PMID 38824202, 2024).
metabolic disease (1 paper, 2020). A congenital disorder (due to inherited enzyme abnormality) or acquired (due to failure of a metabolically important organ) disorder resulting from an abnormal metabolic process. "One candidate gene was methyltransferase-like 8 (METTL8), which has been associated with metabolic disease in humans, body weight in chicken and myogenic differentiation by influencing myogenic gene expression (SRF and MEF2) in mouse." (PMID 33370292, 2020). "METTL8 is identified as a new mRNA m3C writer enzyme, and plays a crucial role in myogenic differentiation and metabolic disease." (PMID 33370292, 2020).
METTL8 also shares sentences with these, for which no sentence is quoted: cholangiocarcinoma (1 paper); colon cancer (1); hepatocellular carcinoma (1); oligodendroglioma (1); ovarian serous cystadenocarcinoma (1); Skeletal muscle atrophy (1); stomach adenocarcinoma (1).